AHR (aryl hydrocarbon receptor)
Diseases named in the same sentence as AHR in open-access papers (continued):
Sharing a sentence is not in itself a finding about the gene and the disease.
COVID-19 (continued). "With the emergence of the COVID-19 pandemic, studies suggest that AHR activation may contribute pro-inflammatory responses, potentially exacerbating cytokine storm in SARS-CoV-2 infection." (PMID 40949107, 2025). "Additionally, lipopolysaccharide (LPS)-induced inflammation serves as a secondary trigger for AHR activation, compounding the severity of COVID-19." (PMID 40949107, 2025). "Collectively, these findings underscore the therapeutic promise of targeting AHR in COVID-19." (PMID 40949107, 2025). "AHR-targeted therapies, including the use of antagonists, may offer therapeutic promise for mitigating cardiometabolic complications in COVID-19." (PMID 40949107, 2025). "COVID-19 could increase the presence of other pathogens and comorbidities that activate AhR via IDO-1-dependent mechanisms." (PMID 38802702, 2024). "Interestingly, the AHR level had positive correlations with the SpO2 level at admission in patients with COVID-19." (PMID 38932276, 2024). "Consistent with the AHR gene’s known role in regulating immune and inflammatory responses, AHR expression demonstrated a trend towards down-regulation in patients with severe COVID-19 compared to those with a moderate infection." (PMID 38932276, 2024). "We found a mild upregulation of AhR in COVID-19 patients, which is in line with previous data." (PMID 38474725, 2024). "Indeed, in fatal COVID-19 AHR was localized in the nucleus of IDO2-expressing cells, indicative of its transcriptional activity, and therefore likely driving IDO2 expression." (PMID 37506544, 2023). "Thus, a disturbed Trp metabolism involving increased proinflammatory activity of KA and possibly also FICZ and mediated by activation of the AhR and PARPs are likely to be at the centre of the pathophysiology of infectious diseases, including COVID-19." (PMID 37486805, 2023). "Here, SARS-CoV-2 can also gain access through dipeptidyl peptidase-4 (DPP4) that is inhibited from activated AhR, which could explain the apparent protection of smokers from COVID-19." (PMID 35203299, 2022). "Kynurenic acid, a KP metabolite, may regulate sex-specific immune responses in COVID-19 by activating the aryl hydrocarbon receptor (AHR)." (PMID 35568706, 2022). "AHR activation may be a strategy by coronaviruses to evade antiviral immunity, and pharmacological inhibition of AHR has been proposed as a COVID-19 therapy." (PMID 35568706, 2022). "Kynurenine signaling through the AHR may induce cell senescence andcontribute to aging-related pathologies of the musculoskeletal system, which can also complicate COVID-19 and PACS." (PMID 35740354, 2022). "Considering that coronaviruses could activate the AhR signaling pathway after entry into cells, a promising treatment for both COVID-19 and tissue fibrosis may be achieved by targeting the tryptophan-AhR pathway." (PMID 35656117, 2022). "Therefore, AhR activation by IDO1-derived tryptophan metabolites in patients with severe COVID-19 can be regarded as a biological defense mechanism against severe infection." (PMID 35463998, 2022). "Taken together, these findings suggest that AHR signaling is upregulated in COVID-19 patients." (PMID 34446714, 2021). "Interestingly, regarding COVID-19, several nutraceuticals are functional antagonists of AhR and thereby their food intake has been postulated as a potential modulator of COVID-19 severity." (PMID 34356384, 2021). "Increased expression of this transcriptional regulatory factor in response to the SARS-CoV-2 infection interfered with antiviral immunity in the host, as AHR suppressed production of type I interferons in the COVID-19 patients and increased SARS-CoV-2 replication in host cells." (PMID 34975885, 2021). "In particular, the expression of KYN in COVID-19-children was lower than in healthy children, but much higher than in COVID-19-adults, suggesting that AhR was still active and the SARS-CoV-2-induced immune response/inflammation processes was still under the control in COVID-19-children." (PMID 34335977, 2021).
COVID-19 (continued). "Given that the IDO-Kyn-AhR pathway is activated in COVID-19 patients, the use of inhibitors of IDO and/or AhR might be beneficial to reduce or prevent bone and muscle loss in this disease." (PMID 34621138, 2021). "It is possible that KA production, despite occurring in both sexes, could elicit a specific immune response and worse clinical outcomes through AhR activation in male COVID-19 patients." (PMID 34230210, 2021). "Activation of the immunoregulatory cytoplasmic transcription factor aryl hydrocarbon receptor (AHR) may also result in hypermethylation that contributes to COVID-19 pathogenesis." (PMID 34691068, 2021). "Inhibiting Trp-Kyn and/or AhR signaling may represent a novel therapeutic approach for preventing COVID-19-dependent musculoskeletal health and other age-related diseases." (PMID 34621138, 2021). "Further investigation into the relevance of KA, KAT, and AhR activation in COVID-19 and the role of glutamate in clinical outcomes will be of utmost importance, particularly for understanding the sex-specific differences in immune response and patient outcomes." (PMID 34230210, 2021). "Indeed, the analysis of single-cell RNA-seq from lung tissue detected increased expression of AHR and AHR transcriptional targets, suggesting AHR signaling activation in SARS-CoV-2-infected epithelial cells from COVID-19 patients." (PMID 34446714, 2021). "As AhR activation primes platelets for coagulation and aggregation, as well as increasing thrombin and fibrin (ogen), clearly increased AhR activation will contribute to COVID-19 fatalities." (PMID 32867244, 2020). "Selected key agents of AHR used in therapeutics that may have effect in COVID-19." (PMID 40949107, 2025). "Thus, it appears reasonable to speculate that 5-hydroxytryptophan contributes to AhR-mediated calibration of inflammatory cytokine production during COVID-19, as well as to T cell exhaustion characteristic of severe SARS-CoV2 infection." (PMID 39085233, 2024). "Furthermore, it has been postulated that AHR activation may be the culprit behind the COVID-19-mediated cytokine storm." (PMID 34691068, 2021). "Our data suggest that smokers could present AhR-dependent upregulation of ACE2 in the oral cavity, which could increase susceptibility to SARS-CoV-2 infection, and therefore increase the risk of contracting severe symptoms of COVID-19." (PMID 34299289, 2021). "Therefore, pharmacologic AHR blockade approaches may be effective to enhance host antiviral immunity and reduce viral replication in COVID-19 patients." (PMID 34975885, 2021). "AhR antagonists may thus also provide a novel approach for the treatment of COVID-19 patients." (PMID 32957545, 2020). "Therefore, it remains to be seen whether AhR antagonism or agonism would be the most promising therapeutic strategy in COVID-19." (PMID 33322584, 2020). "By elucidating the molecular mechanisms of AHR activation in SARS-CoV-2 infection, this review builds a compelling case for therapeutic modulation of AHR as a precision medicine approach against COVID-19." (PMID 40949107, 2025). "This study investigated the relationships between gene expression of AHR, FFAR2, FXR, and TGR5, and COVID-19 outcomes in patients with MAFLD." (PMID 38932276, 2024). "Our findings highlight the potential modulatory roles of these genes, particularly AHR and FXR, in both COVID-19 severity and MAFLD presentation." (PMID 38932276, 2024). "While AHR expression remained largely unchanged in MAFLD patients, those with COVID-19 and MAFLD who displayed down-regulated AHR exhibited higher INR and PT levels (coagulation parameters)." (PMID 38932276, 2024). "Continuing the exploration of the AHR within the context of COVID-19 and MAFLD, research suggests a potential proviral and profibrotic role for AHR." (PMID 38932276, 2024). "For instance, AHR has been reported to contribute to the pathogenesis of SARS-CoV-2 due to its role in mucus production, inducing hypoxia in COVID-19 patients." (PMID 37672505, 2023).
COVID-19 (continued). "After treatment with AHR antagonists in vitro, it was found that the replication of HCoV-229E, the pathogen of the common cold, and SARS-CoV-2, the pathogen of COVID-19, was inhibited to some extent." (PMID 36829212, 2023). "Similar to our findings in fatal COVID-19, we found that the AHR was localized in the nucleus of IDO2-positive cells, in line with the concept that AHR is driving IDO2 expression." (PMID 37506544, 2023). "Therefore, AHR antagonists could be prophylactic and therapeutic agents in COVID-19 severity." (PMID 36114383, 2022). "In this last case, they also support Liu’s hypothesis that states that activated AhR drives the increase in mucin production in lung cells, thus proposing this transcription factor as a possible therapeutic target for relieving respiratory symptoms in COVID-19-affected patients." (PMID 35203299, 2022). "More surprisingly, thanks to the inhibitory effect of PCB on NOX activity and aryl hydrocarbon receptor (AhR) agonism, PCB is suggested as a potential nutraceutical method to reverse nervous system injury induced by COVID-19." (PMID 35726224, 2022). "The expression of genes involved in tryptophan metabolism, including ACE2, AHR, CARD9, and IL22, was downregulated in the ileum of critical COVID-19 patients who required a colonoscopy." (PMID 36035409, 2022). "After comparing the collected genes, 460 host factors common to COVID-19 and dengue were found, including MMP2, PDF, PFKP, SLC25A3, IGF1, CCL4, TLR4, and AhR, and further analysis of interaction networks was performed." (PMID 34394108, 2021). "The AhR is overexpressed in coronaviruses, including COVID-19 and, as it regulates PARP gene expression, the latter is likely to be activated in COVID-19." (PMID 33063092, 2020). "Furthermore, dexamethasone, a clinical agent used in COVID-19 treatment, exerts partial inhibitory effects on IDO1 and AHR through glucocorticoid receptor-mediated pathways, contributing to reduced cytokine storm severity and enhanced viral clearance." (PMID 40949107, 2025). "Taken together, these findings suggest that AHR, FFAR2, FXR, and TGR5 may play significant roles in the progression of both COVID-19 and MAFLD." (PMID 38932276, 2024). "As [Kyn] at 10 μM does not activate the AhR, it is most likely that AhR activation in COVID-19 is mediated largely by KA." (PMID 37486805, 2023). "However, during the cytokine storm observed in severe COVID-19, KYN mediated AhR activation is considered to be an essential biological response to suppress systemic organ damage, as is mucus secretion in terms of infection defense." (PMID 35463998, 2022). "AhR/Kyn binding boosts the production of Interleukin-6 (IL-6), thus reinforcing the inflammatory state and counteracting the IDO-dependent immune tolerance in the later stage of COVID-19." (PMID 35203299, 2022). "To further investigate AHR signaling in the context of human SARS-CoV-2 infection, we analyzed a scRNA-Seq dataset of bronchoalveolar lavage fluid (BALF) cells from control and COVID-19 patients." (PMID 34446714, 2021). "Thus, activation of the AhR was demonstrated with SARS, MERS, COVID-19, with the mouse hepatitis virus (MHV) model and the pneumovirus RSV." (PMID 33063092, 2020). "The immunity modulators, the aryl hydrocarbon receptor (AhR) and the nuclear NAD+-consuming enzyme poly (ADP-ribose) polymerase 1 (PARP 1) may play a critical role in COVID-19 pathophysiology." (PMID 33063092, 2020). "In addition, AhR activation promoted SARS-CoV-2 infection and replication, limited type I IFN signaling, and up-regulated the expression of ACE2, thus acting as a proviral factor whose inhibition was suggested to be used as a therapeutic approach in COVID-19." (PMID 39057395, 2024). "Since we demonstrated that jasmone antagonized ligand-triggered AhR activity, it may be of particular interest if its application might help to boost antiviral immunity, e.g., after exposure to viruses like HCoV-229E (common cold) or SARS-CoV-2 (COVID-19)." (PMID 37958638, 2023).
COVID-19 (continued). "In addition, the mechanism of gastrointestinal damage in patients with COVID-19 may involve impaired tryptophan metabolism due to the decreased expression of ACE2, AHR, and CARD9 in the small intestinal mucosa." (PMID 36035409, 2022). "Therefore, in the COVID-19 inflammatory environment, it is possible to imagine that AhR engagement is achieved by Kyn activation and/or by a possible IL-6-dependent STAT-3 modulation of AhR gene expression." (PMID 35203299, 2022). "Therefore, considering the link between MAFB/MAF ratio and AHR expression, the proposed involvement of AhR in COVID-19 pathogenesis is well in agreement with our hypothesis on the contribution of MAFB and MAF to severe COVID-19." (PMID 33312178, 2020). "Interestingly, AhR has been shown to be highly activated during coronavirus infections, including MERS-CoV, SARS-CoV-1 and SARS-CoV-2 (responsible for the new outbreak COVID-19)." (PMID 32957545, 2020). "However, in the COVID-19 context, the greater availability of tryptophan will allow for its metabolism through the kynurenine pathway, whose metabolites will induce the expression of the pro-inflammatory IL-1β, IL-10, TNF-α, IL-6 by AHR, further increasing the local and systemic inflammation." (PMID 36293182, 2022). "Evidence supporting the role of AhR in lung physiology, including negative NLRP3 regulation, could provide new COVID-19 therapeutic opportunities based on the AhR and/or other xenobiotic receptor biological functions." (PMID 33916409, 2021).
colorectal cancer (57 papers, 2012 to 2026). A primary or metastatic malignant neoplasm that affects the colon or rectum. "The observed changes in the presented transcripts in phases I–III, as well as those associated with the AhR, indicate their importance for new therapies and directions for preventive measures in colorectal cancer." (PMID 41465541, 2025). "AHR agonists such as I3C were used as a chemopreventive therapy for IBD-associated colorectal cancer." (PMID 37179416, 2023). "Kynurenine has been linked to both breast and colorectal cancers and acts as a major endogenous activator of the aryl hydrocarbon receptor (AhR) which can increase adipocyte proliferation, and tumour progression." (PMID 36038791, 2022). "In this way, I3C exhibits anticancer effects on several colorectal cancer cell lines, causing cell death through AhR activation." (PMID 35678668, 2022). "Diet, loss of aryl hydrocarbon receptor (AhR) expression and their modification of the gut microbiota community composition and its metabolites affect the development of colorectal cancer (CRC)." (PMID 33256731, 2020). "Deficiency of AHR in IECs hampered the ability of intestinal stem cells to restore and differentiate in response to cell injury, having a significant impact on infection resistance and colorectal cancer development." (PMID 37179416, 2023). "AHR-mutants have increased susceptibility to colorectal cancer development and our work provides further mechanistic insight into the cancer protective functions of AHR in colonic epithelial cells by demonstrating a key role for AHR in restricting Yap1-mediated transcriptional activity." (PMID 35383166, 2022). "Without AHR, this process was defective, leading to a prolonged regenerative program at the expense of differentiation, a scenario that may underlie the increased risk of colorectal cancer initiation in AHR deficient mice." (PMID 35383166, 2022). "Furthermore, a high-fat diet combined with loss of AhR in intestinal epithelial cells influenced the development of colorectal cancer." (PMID 33451095, 2021). "For example, TCDD and other AhR activators are associated with colitis and colorectal cancers, BPA is implicated in colorectal cancer, and PAH may lead to digestive tract cancers." (PMID 29021788, 2017). "In colorectal cancer, aryl hydrocarbon receptor (AhR) has recently been shown to play a role in tumorigenesis and has been identified as a potential therapeutic target." (PMID 41155994, 2025). "More recent concepts further implicate the kynurenine–aryl hydrocarbon receptor axis and serine protease–mediated degradation of dependence receptors such as deleted in colorectal cancer and neogenin as additional routes promoting carcinogenesis." (PMID 41502515, 2025). "In the context of IBD and colorectal cancer prevention, this includes nutraceuticals such as kynurenic acid, quercetin, curcumin, and probiotics, which modulate AhR and GPR35 signaling pathways." (PMID 41009721, 2025). "Most recently, formate has been shown to exacerbate colorectal cancer progression via activation of the AhR signalling pathway." (PMID 40756341, 2025). "In an inflammation‐related colorectal cancer model, interruption of Trp‐indole‐AhR signaling resulted in significantly elevated mRNA levels of TNF‐α, IL‐1β, and IL‐6." (PMID 40103267, 2025). "In mice, AHR was shown to suppress colorectal cancer development in an epithelial cell-intrinsic manner." (PMID 40212817, 2025). "These metabolites stimulate the aryl hydrocarbon receptor (AHR) pathway, inhibiting colorectal cancer CRC cell proliferation and colorectal tumorigenesis." (PMID 40428595, 2025). "The AhR expression in cancer cells increased with an increasing colorectal cancer grade, similar to the results obtained for HNSCC." (PMID 38680496, 2024). "Taken together, these data would indicate that AhR directly regulates ATR/CHK1/γH2AX survival response in response to BOLD-100 treatment in BRAFMT colorectal cancer." (PMID 39083088, 2024).